RNU5E-5P (RNA, U5E small nuclear 5, pseudogene)
Gene: Small nuclear RNA gene on chromosome 12 (101,466,705 to 101,466,820, forward strand). Ensembl gene ENSG00000202249.
Homologues: Orthologues: chimpanzee U5 (97% identical), macaque U5 (92% identical), mouse Gm23102 (72% identical), rabbit U5 (72% identical). Paralogues in human: RNU5A-6P (78% identical), RNU5B-4P (76% identical), RNU5E-10P (76% identical), RNU5E-4P (76% identical), RNU5A-3P (72% identical), RNU5E-6P (72% identical), RNU5E-8P (72% identical), RNU5A-4P (72% identical), RNU5A-7P (72% identical), RNU5A-2P (71% identical), RNU5E-7P (70% identical), RNU5F-7P (70% identical), and 13 more.